CYP7A1 (cytochrome P450 family 7 subfamily A member 1)
Description:
A cytochrome P450 monooxygenase involved in the metabolism of endogenous cholesterol and its oxygenated derivatives (oxysterols). Mechanistically, uses molecular oxygen inserting one oxygen atom into a substrate, and reducing the second into a water molecule, with two electrons provided by NADPH via cytochrome P450 reductase (CPR; NADPH-ferrihemoprotein reductase). Functions as a critical regulatory enzyme of bile acid biosynthesis and cholesterol homeostasis. Catalyzes the hydroxylation of carbon hydrogen bond at 7-alpha position of cholesterol, a rate-limiting step in cholesterol catabolism and bile acid biosynthesis. 7-alpha hydroxylates several oxysterols, including 4beta-hydroxycholesterol and 24-hydroxycholesterol. Catalyzes the oxidation of the 7,8 double bond of 7-dehydrocholesterol and lathosterol with direct and predominant formation of the 7-keto derivatives.
Synonyms: CYP7; CP7A; CYPVII
Tractability: Small molecule: a structure with a bound ligand is known; it has a high-quality binding pocket. Antibody: UniProt predicts a signal peptide or a membrane-spanning region. PROTAC: a small molecule that binds it is known.
Target class: Cytochrome P450; Enzyme; Cytochrome P450 family 7A; Cytochrome P450 7A1; Cytochrome P450 family 7
Gene: Protein-coding gene on chromosome 8 (58,490,178 to 58,500,163, reverse strand). Ensembl gene ENSG00000167910.
Subcellular location: Endoplasmic reticulum membrane; Microsome membrane
Pathways (Reactome):
Metabolism: Endogenous sterols; PPARA activates gene expression; Synthesis of bile acids and bile salts; Synthesis of bile acids and bile salts via 27-hydroxycholesterol; Synthesis of bile acids and bile salts via 7alpha-hydroxycholesterol
Gene Ontology:
Molecular function: 24S-hydroxycholesterol 7-alpha-hydroxylase activity; cholesterol 7-alpha-monooxygenase activity; heme binding; iron ion binding; monooxygenase activity; oxidoreductase activity, acting on paired donors, with incorporation or reduction of molecular oxygen
Biological process: bile acid biosynthetic process; cellular response to glucose stimulus; regulation of bile acid biosynthetic process; cellular response to cholesterol; cholesterol catabolic process; cholesterol homeostasis; sterol metabolic process; bile acid metabolic process; negative regulation of collagen biosynthetic process; negative regulation of fatty acid biosynthetic process; positive regulation of cholesterol biosynthetic process; response to ethanol
Cellular component: endoplasmic reticulum membrane; intracellular membrane-bounded organelle
Genetic constraint (gnomAD): Loss-of-function variants: 25 observed, 42.58 expected, observed/expected ratio (o/e) 0.59, 90% interval 0.43 to 0.82. The upper end of that interval is the gene's LOEUF score, 0.82, which puts it in group 3 of 6, group 1 being the genes least tolerant of losing a copy. Missense variants: 630 observed, 635.74 expected, observed/expected ratio (o/e) 0.99, 90% interval 0.93 to 1.06. Synonymous variants: 227 observed, 233.43 expected, observed/expected ratio (o/e) 0.97, 90% interval 0.87 to 1.09.
Homologues: Orthologues: chimpanzee CYP7A1 (99% identical), macaque CYP7A1 (96% identical), rat Cyp7a1 (82% identical), dog CYP7A1 (82% identical), rabbit CYP7A1 (82% identical), mouse Cyp7a1 (82% identical), guinea pig CYP7A1 (80% identical), pig CYP7A1 (80% identical), zebrafish cyp7a1 (65% identical), tropical clawed frog cyp7a1 (63% identical). Paralogues in human: CYP7B1 (39% identical), CYP39A1 (23% identical).
Diseases named in the same sentence as CYP7A1 in open-access papers:
CYP7A1 is named in the same sentence as 95 diseases in open-access papers, as found by Europe PMC text mining. Sharing a sentence is not in itself a finding about the gene and the disease. The quoted sentences say what the papers report.
Hypercholesterolemia (63 papers, 2006 to 2025). An increased concentration of cholesterol in the blood. "CYP7A1 deficiency in humans can lead to hypercholesterolemia, further underscoring the pivotal role of this enzyme in lipid homeostasis." (PMID 39594419, 2024). "It has been reported that deficiency of Cyp7a1 leads to hypercholesterolemia, while plasma cholesterol levels are reduced in mice overexpressing Cyp7a1." (PMID 36838229, 2023). "Deficiency of Cyp7a1 results in a strikingly decreased output of BAs, and it was related to hypercholesterolemia and premature atherosclerosis." (PMID 36594057, 2023). "Mutations in the CYP7A1 gene in adult males cause only mild hypercholesterolemia and early-onset gallstone disease, suggesting that when the classical pathway initiated by CYP7A1 is defective, the alternative BA synthesis pathway is activated to produce BAs." (PMID 37120573, 2023). "It was reported that CYP7A1 deficiency in human results in a hypercholesterolemia and premature gallstone disease, and that mice overexpressing Cyp7a1 have a decreased levels of plasma cholesterol." (PMID 36211528, 2022). "Specifically, KO mice livers upregulated the Cyp7a1 (Cytochrome P450 Family 7 Subfamily A Member 1) gene that has an important role in cholesterol and bile acid metabolism and is associated with hypercholesterolemia." (PMID 36142337, 2022). "In fact, both CYP7A1 deficiency in humans and CYP7A1 knockout mice exhibited hypercholesterolemia and reduced fecal BA levels." (PMID 35682726, 2022). "This assumption was supported by the negative correlation between circulating cholesterol and the expression level of hepatic cyp7a1, as cyp7a1 deficiency has been reported to lead to hypercholesterolemia." (PMID 33967831, 2021). "CYP7A1 is the key enzyme that catalyzes the initial step in cholesterol catabolism and bile acid synthesis, and a deficiency of CYP7A1 is associated with hypercholesterolemia." (PMID 32253466, 2020). "In this study, we show that hepatic TFEB deficiency reduces hepatic CYP7A1 expression and sensitizes mice to hypercholesterolemia upon WD challenge." (PMID 32681035, 2020). "Human CYP7A1 gene defect can cause cholesterol accumulation in the liver, which has been associated with hypercholesterolemia." (PMID 26242978, 2015). "Genetic deficiencies of CYP7A1 in humans are associated with hypercholesterolemia and the accumulation of cholesterol in liver." (PMID 22607622, 2012). "Genetic variations in the CYP7A1 gene have been associated with metabolic disorders of cholesterol and bile acids, including hypercholesterolemia, hypertriglyceridemia, arteriosclerosis, and gallstone disease." (PMID 16709249, 2006). "However, the specific mechanism underlying the effect of taurine on CYP7A1 remains poorly understood, and many aspects of the potential of taurine in addressing hypercholesterolemia remain unexplored." (PMID 39199235, 2024). "Consequently, CYP7A1 mutation in humans causes hypercholesterolemia, hypertriglyceridemia, and accumulation of cholesterol in the liver, despite induction of the alternative pathway." (PMID 35614477, 2022). "Interestingly, some mutations identified in the human CYP7A1 gene are correlated with greater prevalence of hypercholesterolemia and atherosclerosis." (PMID 34281217, 2021). "Nevertheless, whole-exome sequencing has revealed that mutations in the lysosomal acid lipase A (LIPA), ATP-binding cassette sub-family G member 5 and 8 (ABCG5/8), and cholesterol 7 alpha-hydroxylase (CYP7A1) genes phenotypically cause hypercholesterolemia similar to FH in the recessive status." (PMID 33732287, 2021).
Hypercholesterolemia (continued). "Of note, a mild hypercholesterolemia has already been observed due to Keap1 deletion in WT mice and was attributed to a reduced expression of the Cyp7a1 (cytochrome P450 family 7 subfamily A member 1) gene, which encodes for an enzyme involved in the biotransformation of cholesterol into bile acids." (PMID 34298930, 2021). "Human patients with CYP7A1 mutations developed hypercholesterolemia and premature atherosclerosis." (PMID 32681035, 2020). "Cyp7a1-deficient mice display hypercholesterolemia, fatty liver, and hepatomegaly." (PMID 22912762, 2012). "Many studies have reported that activating Cyp7a1 to promote bile acid synthesis can reduce high-fat diet-induced hypercholesterolemia." (PMID 40565139, 2025). "It has been previously reported that taurine ameliorates blood cholesterol accumulation in hypercholesterolemia and promotes cholesterol catabolism to bile acids by increasing CYP7A1 gene expression and activity." (PMID 39199235, 2024). "The dietary taurine facilitated cholesterol catabolism by improving CYP7A1, thereby restoring serum cholesterol levels to normal and ameliorating hypercholesterolemia induced by high cholesterol diet." (PMID 39199235, 2024). "Accordingly, the CYP7A1 enzyme participates in cholesterol catabolism and bile acid homeostasis, which play important roles in the development of hypercholesterolemia and dyslipidemia." (PMID 38540230, 2024). "First, the previously known mechanism by which taurine improves hypercholesterolemia by increasing CYP7A1 and promoting cholesterol catabolism to bile acids was confirmed." (PMID 39199235, 2024). "ABCG5/8 transported cholesterol by activating the transcription of LXR, and FXR regulated cholesterol via the SR-B1/CYP7A1/FXR pathway to alleviate hypercholesterolemia in high-fat-diet-fed rats." (PMID 37299563, 2023). "In contrast, the lack of an LXR site in the human CYP7A1 promoter prevents hepatic induction of human CYP7A1 by high cholesterol, resulting in increased hypercholesterolemia when fed a HFD." (PMID 35614477, 2022). "It was found that FA attenuates HFD-induced hypercholesterolemia by activating CYP7A1, the rate-limiting enzyme of classic BAs biosynthesis, via a non-FXR signaling." (PMID 36211528, 2022). "The regulation of CYP7A1 is important for the prevention and treatment of hypercholesterolemia and atherosclerosis because overexpression of CYP7A1 was shown to improve hypercholesterolemia and atherosclerosis in animal models." (PMID 34445273, 2021). "We show that TFEB induces cholesterol 7α-hydroxylase (CYP7A1) in human hepatocytes and mouse livers and prevents hepatic cholesterol accumulation and hypercholesterolemia in Western diet-fed mice." (PMID 32681035, 2020). "In our previous study, suppressing the feeding rhythm induced hypercholesterolemia by advancing the phase of CYP7A1 by altering the circadian oscillation of DBP in rats." (PMID 30379940, 2018). "Many studies on the hypercholesterolemia rat and mouse have revealed that taurine increases the mRNA expression and activity of CYP7A1, and the same improvement has also been observed via the in vitro experiment." (PMID 28302129, 2017). "Many in vivo studies with hypercholesterolemia rat, mouse and hamster reveal that the cholesterol-lowering effect of taurine is carried out by enhancing CYP7A1 activity or gene expression and fecal bile acid excretion, while in vitro researches are few." (PMID 28302129, 2017). "EGFR activation in the Mig-6 deletion mice downregulated CYP7A1 protein expression resulting in hypercholesterolemia." (PMID 28053990, 2016). "Dietary RSV has been shown to increase the expression of hepatic CYP7A1 and to ameliorate hypercholesterolemia in high-fat-fed C57BL/6J mice." (PMID 27048804, 2016).
Hypercholesterolemia (continued). "The regulation of CYP7A1 gene expression is a very important strategy for preventing and improving hypercholesterolemia and atherosclerosis." (PMID 25144734, 2014). "Patients presenting with genetic defects in the CYP7A1 exhibit marked hyperlipidemia, including hypercholesterolemia." (PMID 23209629, 2012). "Female-biased expression was also observed for CYP7A1, which is activated by drugs used to treat hypercholesterolemia." (PMID 21858147, 2011). "As Cyp7a1 mRNA levels were increased by high-dose zalfermin, we speculate that zalfermin may improve hypercholesterolemia by stimulating cholesterol flux into bile acids." (PMID 41150667, 2025). "Taurine can ameliorate hypercholesterolemia by facilitating cholesterol efflux and increasing cytochrome P450 7A1 (CYP7A1) without clear underlying molecular mechanisms." (PMID 39199235, 2024). "Previous studies have shown FA could attenuate high-fat diet-induced hypercholesterolemia by activating CYP7A1 to promote bile acid synthesis." (PMID 39594419, 2024). "Conversely, upregulation of CYP7A1 can counteract cholesterol diet-induced hypercholesterolemia by preventing hepatic cholesterol accumulation and reducing the proliferation of apoB-containing lipoproteins in plasma, facilitated by augmented SREBP-mediated LDL receptor transcription." (PMID 39204178, 2024). "Interestingly, liver-specific pVHL knockout mice displayed hypercholesterolemia, an effect that was HIF2α dependent, and presumably involved an inhibition of Cyp7a1-mediated conversion of cholesterol into bile acids." (PMID 34055796, 2021). "CYP7A1 may also be involved in the anti-hypercholesterolemia effect of plant extracts and in the hepatotoxicity caused by certain anti-tuberculosis drugs." (PMID 34941783, 2021). "The conversion of cholesterol to bile acids contributes to the elimination of TC from the body; thus, the increase in activity of CYP7A1 may be beneficial in subjects with hypercholesterolemia and CVD." (PMID 34684480, 2021). "Although BA metabolism plays a critical role in CS homeostasis and the onset of hypercholesterolemia, Cyp7a1 deficiency is not always associated with reduced tissue CS turnover or hypercholesterolemia." (PMID 34281217, 2021). "Our previous study showed that irregular feeding induced hypercholesterolemia by disrupting the circadian oscillations of several clock genes and shifted the peak of the circadian oscillation of cholesterol 7 alpha-hydroxylase (CYP7A1)." (PMID 30379940, 2018). "Increasing Cyp7a1 expression has been postulated as a potential treatment for hypercholesterolemia." (PMID 29896121, 2018). "L. edodes may help regulate lipid metabolism, suggesting that this fungus ameliorates hypercholesterolemia in mice by regulating CYP7A1 expression in the liver." (PMID 24255670, 2013). "Ablation of CYP7a1 in mice also results in hypercholesterolemia." (PMID 23209629, 2012). "Notably, previous studies have reported FA could attenuate high-fat diet-induced hypercholesterolemia by activating CYP7A1 to promote bile acid synthesis." (PMID 39594419, 2024). "Deficiency in CYP7A1 in humans leads to significant metabolic aberrations, including impaired conversion of cholesterol to BAs, accumulation of hepatic cholesterol, reduction of LDL receptor expression, exacerbated hypercholesterolemia, and diminished statin response." (PMID 39204178, 2024).
Hypercholesterolemia (continued). "However, rifaximin induced hepatic cytochrome P450 7A1 (CYP7A1) enzyme, the gatekeeper of bile acid synthesis, which suggests that increased bile acid synthesis may have protected the mice from hypercholesterolemia." (PMID 35159123, 2022). "Thus, an oligogenic form of hypercholesterolemia is probably present in this family and high levels of LDL-C could be caused by the cumulative effect of LRP6 and CYP7A1 variants, which is aggravated by the LDLRAP1 variant." (PMID 35323704, 2022). "Therefore, we suggest that the beneficial effects of mulberry leaves on HC-diet induced hypercholesterolemia may be partially mediated through the regulation of hepatic CYP7A1 expression." (PMID 33994909, 2021). "Phytosterol diosgenin (DG) notably decreases hepatic cholesterol through increasing hepatic CYP7A1 and prohibiting FXR-mediated signaling, thus contributing to cholesterol elimination and alleviating HFD-induced hypercholesterolemia." (PMID 39204178, 2024). "The present work elucidates a mechanism by which bone‐derived SAA3 inhibits the expression of CYP7A1 by binding to TLR4 on hepatocytes and thereby phosphorylates c‐Jun, which leads to hypercholesterolaemia in Tsc1Dmp1 mice." (PMID 38613835, 2024). "Based on the reduction in Cyp7a1 enzyme in our LFD-AR mice, we expected to see hypercholesterolemia; however, plasma cholesterol, triglycerides, and high-density lipoproteins were unaffected by Aroclor 1260 exposure particularly in the LFD-fed group." (PMID 37426695, 2023). "Taurine ameliorated hypercholesterolemia in rats fed a high cholesterol diet by directly enhancing the hepatic expression of BHMT and OATP2, which modulated the SHP and induced CYP7A1 and CYP8B1, thereby promoting cholesterol catabolism and lowering blood cholesterol levels." (PMID 39199235, 2024). "It has also been reported that rats with NS accompanied with hypercholesterolemia lack Cyp7a1 upregulation, while rats that have equally high hypercholesterolemia due to a high fat diet do not present with NS and show marked elevation of Cyp7a1 RNA levels." (PMID 25361754, 2014). "CYP7A1 is the initial and rate‐limiting enzyme in the bile acid biosynthesis process, and the lack of CYP7A1 impeded the clearance of serum cholesterol, resulting in progressive hypercholesterolemia in Tsc1Dmp1 mice, which was observed as early as 3 months of age." (PMID 38613835, 2024). "However, CYP7A1 KO mice show that inhibition of CYP7A1 does not result in hypercholesterolemia as cholesterol is eliminated by their secretion into bile by the cholesterol transporter ATP-binding cassette transporter G (ABCG5) and G8 (ABCG8)." (PMID 38180064, 2024). "In conclusion, FA activates CYP7A1 through non-FXR signaling, which on the one hand effectively prevents hypercholesterolemia, and on the other hand leads to secondary BAs elevation in plasma." (PMID 36211528, 2022). "However, human CYP7A1 does not contain LXRE, and is thus shown not to be upregulated by LXRa agonists and seems to be more affected by diet-induced hypercholesterolemia due to its inability to convert cholesterol into bile salts." (PMID 36836631, 2023).